IL6 (interleukin 6)
Diseases named in the same sentence as IL6 in open-access papers (continued):
Sharing a sentence is not in itself a finding about the gene and the disease.
respiratory diseases (continued). "Furthermore, it has been demonstrated that periodontal infections lead to the production of IL-6 and other inflammatory markers in respiratory epithelial cells, suggesting a possible connection between dental health and the consequences of respiratory diseases." (PMID 40647649, 2025). "We then conducted two subgroup analyses: the first segregated the control group into healthy patients, and those with other respiratory diseases (ORD), and the second addressed three different interleukins separately (IL-6, IL-5, IL-17)." (PMID 40431146, 2025). "In multiple animal models of respiratory diseases, the treatment with XC221GI led to controlling the levels of CXCL9, CXCL10, CXCL11, IL-6 and IL-8, and to decrease of extent of the pathogen-driven cytokine storm." (PMID 37214455, 2023). "Previous studies have shown that IL-6 production is involved in the airway inflammatory response and PM2.5-induced respiratory diseases." (PMID 34884542, 2021). "Serum levels of IL-6, VEGF and TNF-a were significantly different between participants with active TB disease and those with other respiratory diseases." (PMID 28859607, 2017). "Therefore, understanding the roles of IL-6, IL-13, IFN-γ, and TNF-α is essential for developing an effective vaccine and treatment against SARS-CoV-2 and other respiratory diseases." (PMID 38060612, 2023). "In addition, IL-6, IL-1β, and TNF-α are proinflammatory cytokines that participate in many inflammatory responses of the lung, and studies have shown that the abnormal expression of IL-6, IL-1β, and TNF-α is related to the pathogenesis of respiratory diseases." (PMID 34135982, 2021). "No significant increases were found for IL-1 and IL-6 between controls and respiratory disease in general as well as different disease groups." (PMID 27938364, 2016). "Together, our results suggest that SCFP supplementation may increase systemic IL-6 responses in calves with bovine respiratory disease, but may not impact other markers of the acute-phase response." (PMID 34673945, 2021). "Furthermore, the release of IL-8, IL-6 and TNF-α at the basolateral compartment simulate the release of inflammatory factors from the epithelium into the bloodstream observed in animal and human (childhood) respiratory diseases." (PMID 32747652, 2020). "Patients with respiratory disorders without CPA had also significantly higher values for IFN-γ, IL-1b, IL-6, IL-8, and TNF-α compared to healthy individuals." (PMID 30333797, 2018). "While expression of IL-6 and TLR-4 was not altered in our study, the pattern of expression suggests that animals that acquired BRD were actively combating respiratory disease agents at arrival and did not possess active molecular pathways necessary for mitigating prolonged inflammation." (PMID 31929561, 2020). "Levels of IL-1b, IL-6, IL-8, TNF-α, and IFN-γ were significantly higher in CPA patients compared to healthy individuals (p < 0.001 and p = 0.008, respectively), but not different than in patients with respiratory disorders without CPA." (PMID 30333797, 2018).
adenocarcinoma (66 papers, 1998 to 2025). A common cancer characterized by the presence of malignant glandular cells. "The ensuing circle plot reveals that a strong association exists through IL-6 signaling between macrophages and the gastric epithelium as well as adenocarcinoma cells." (PMID 38422751, 2024). "A similar trend was found in the validation study using independent stage I adenocarcinoma patients; patients with high circulating levels of both IL-6 and IL-17A had an increased risk of poor prognosis." (PMID 28402963, 2017). "STAT3 is persistently activated in about 50% of NSCLCs, especially in adenocarcinomas harboring activating mutations in EGFR which activate the gp130/JAK/STAT3 pathway by means of IL-6 upregulation." (PMID 27835873, 2017). "Indeed, the main source of IL-6 signaling in this setting are macrophages (see heat map), which in turn show the largest association with gastric epithelial and adenocarcinoma cells." (PMID 38422751, 2024). "Stratification analysis showed that IL-6 rs1800795 greatly increased the NSCLC risk in females and adenocarcinoma subtypes, whereas IL-1β rs16944 largely decreased the NSCLC risk for males, patients aged < 55, and nonsmokers." (PMID 38103126, 2024). "We also confirmed increased expression of the IL-6 and NFκB genes, as well as upregulated IL-6 antigen and NFκB signaling in adenocarcinoma tissue." (PMID 39337548, 2024). "Proinflammatory nuclear factor kappa B (NFκB) signaling as well as interleukin 6 (IL-6) and S100 protein levels were upregulated in adenocarcinoma compared with nearby healthy colon tissue." (PMID 39337548, 2024). "Regarding inflammation markers, we examined the frequency of proinflammatory IL-6 and S100 in the adenocarcinoma tissue of the colon." (PMID 39337548, 2024). "Markers such as TNFα, IL-6, and Ataxin-10 were observed to be elevated in cardiac tissue of colon-26 (C26) adenocarcinoma mice." (PMID 35326491, 2022). "First, we examined the expression of NF-κB components, AICDA, Akt, JAK2/STAT3, and IL6 in PC9 (adenocarcinoma with the EGFR exon 19 deletion) and PC9/GR (adenocarcinoma with the EGFR-TKI-resistant with T790M mutation) cells, using Western blotting and RT-PCR." (PMID 35740609, 2022). "The mRNA expression of IL-6 was significantly higher in the adenocarcinoma group than that in the normal group." (PMID 36110250, 2022). "Primary prostatic cultures of normal and adenocarcinoma cells treated with 1,25(OH)2D displayed lower expression levels of interleukin-6 (IL-6), accompanied to p38 MAPK inactivation." (PMID 32560347, 2020). "In the present study, plasma IL-6 levels in patients with adenocarcinoma ranged from 6 to 8 ng/mL, an increase of three or more times." (PMID 33167343, 2020). "First, we made a urethane-induced adenocarcinoma model to explore the mechanism of E2 stimulation of IL6 expression." (PMID 29970138, 2018). "Colonic tissue (adenocarcinoma [cases] healthy mucosa [controls]) was subjected to quantitative PCR (hepcidin, iron transporters and IL-6) and Perls’ iron staining." (PMID 24872837, 2014). "Our results demonstrate that endothelial cell-secreted IL-6 defines the growth of adenocarcinomas in preclinical models." (PMID 24533454, 2014). "In this work, using a proinflammatory cytokine array, we have shown that adenocarcinoma C-26 cells can secrete and progressively accumulate in the CM high concentrations of at least two cytokines, IL-6 and MCP-1." (PMID 24967341, 2014). "Caco-2 cells, an epithelial adenocarcinoma cell line, have receptors for IL-6 at both poles and for IL-1 at the basolateral surface and to a lesser extent at the apical pole." (PMID 22570785, 2012). "We chose C26 adenocarcinoma, which exhibits increased circulating levels of IL-6 that coincide with muscle wasting." (PMID 21799891, 2011). "IL-6 frequency was increased in the adenocarcinoma tissue of the colon (p < 0.05)." (PMID 39337548, 2024).
adenocarcinoma (continued). "Interestingly, the PD-L1 expression on adenocarcinomas-conditioned moDCs positively correlated with the phagocyte activity, IL-6 production, and IL-10 producing CD4+CD25+ T cell activation." (PMID 36194602, 2022). "However, we found that adenocarcinomas-educated moDCs’ IL-6 production positively correlates with IL-10 producing T cell activator capacity by monocyte-derived cells." (PMID 36194602, 2022). "Also in this case we found the same trends and consistent significance of IL-6 (adenocarcinoma-group p = 0.002 and squamous-group p = 0.038) and IFN-γ (adenocarcinoma-group p = 0.003 and squamous-group p = 0.010)." (PMID 34035415, 2021). "Similarly, cigarette smoke condensate suppressed IL-6, IL-8 and mitogen activated protein kinase responses to H. influenzae in the adenocarcinoma A549 alveolar cell line." (PMID 31113421, 2019). "For instance, IL-6 regulates MMP 10 through JAK2/STAT3 signaling in adenocarcinomas." (PMID 30220965, 2018). "Well-differentiated adenocarcinomas tend to express IL-6 in stromal fibroblasts." (PMID 23593346, 2013). "IL-12 treatment of IL-12R+ neoplastic cells isolated from primary adenocarcinoma (n = 6) inhibited angiogenesis in vitro through down-regulation of different pro-angiogenic genes (e.g. IL-6, VEGF-C, VEGF-D, and laminin-5), as assessed by chorioallantoic membrane (CAM) assay and PCR array." (PMID 19582164, 2009). "However, the detection of a markedly increased level of IL-6 in pleural fluid argues against a diagnosis of adenocarcinoma." (PMID 9528833, 1998). "The qPCR analyses demonstrated increased inflammatory IL-6, the receptor for advanced glycation end products (RAGE), and NFκB gene expression in the adenocarcinoma tissue compared to the bordering healthy tissue of the colon (p < 0.05)." (PMID 39337548, 2024). "There was also a significant positive correlation between IL-6 and MMP-9 in adenocarcinoma and SqCC, with correlation coefficients of 0.53 and 0.49, respectively." (PMID 34439874, 2021). "The pairwise correlation revealed a significant positive correlation between IL-6 and MMP-9 in adenocarcinoma and SqCC, with correlation coefficients of 0.53 and 0.49, respectively." (PMID 34439874, 2021). "Particularly intriguing is the correlation between IL-6 and MMP-9 in patients with adenocarcinoma and SqCC, with correlation coefficients of 0.53, 0.49, respectively, which undoubtedly influences TME processes." (PMID 34439874, 2021). "4’-geranyloxy-ferulic acid and auraptene, both natural compounds isolated from plants, enhanced apoptosis in adenocarcinoma in AOM/DSS mice through suppression of NFκB, TNFα, NRF2, IL-6 and IL-1β." (PMID 31905803, 2019). "Chromatin immunoprecipitation assays in tumors showed that BRD4 is recruited at the IL6 promoter and that (+)-JQ1 treatment impairs BRD4 occupancy, suggesting that (+)-JQ1 plays a primary role in hindering IL6 expression in C26 adenocarcinoma tumors." (PMID 29167426, 2017). "We measured the concentration of IL-6, IL-10, TNF-α, MCP-1, INF-γ, and IL-12p70 secreted in the conditioned medium (CM) by the murine colon C-26 adenocarcinoma cells." (PMID 24967341, 2014). "Moreover, we isolated two more paired NGFs and CAFs (CAF3: poorly differentiated adenocarcinoma and CAF4: poorly differentiated adenocarcinoma) and compared IL-6 secretion between NGFs and CAFs." (PMID 35615263, 2022). "Furthermore, microenvironment changes including endogenous IL-6 expression, MMP-9 production and other pro-inflammation cytokines upregulation fulfil complicated and comprehensive function in the process of adenocarcinoma transdifferentiating into NEC." (PMID 34956090, 2021). "We investigated whether plasma IL-6 concentration correlates with the NLR and SII values and the expression of IL-6 was evaluated in biopsies of adenocarcinoma patients." (PMID 33167343, 2020).
adenocarcinoma (continued). "Intestinal epithelial cells from both IBD and normal controls have receptors for IL-1, IL-6, and GM-CSF, but not for TNFα, although they have been detected on adenocarcinoma cell lines." (PMID 22570785, 2012). "Hochuekkito significantly suppressed the secretion of IL-6 from RAW264.7 cells, but it did not inhibit the production of IL-6 from C26 adenocarcinoma cells (data not shown)." (PMID 23326296, 2012). "IL-6 expression was independent of the adenocarcinoma subtype." (PMID 33167343, 2020).
hematological malignancies (63 papers, 2009 to 2026). "Previous research has found that invasive pulmonary aspergillosis causes an increase in Th1/17 cytokines in individuals with hematological diseases and that IL-6 and IL-8 are strongly related to invasive pulmonary aspergillosis." (PMID 36319826, 2022). "There may be several causes of septic shock in children with an underlying disease of hematological malignancy that presents with excessively high IL-6 levels." (PMID 40136690, 2025). "We evaluated prognostic potential of IL-6, IL-8, and several fungal biomarkers for overall mortality in a high-risk cohort of hematological malignancy patients (>80% of cases had received mold-active antifungals at the time of sampling) undergoing bronchoscopy for suspected pulmonary mold infection." (PMID 31428097, 2019). "In conclusion, high blood and BAL IL-8 and IL-6 levels at the time of bronchoscopy and, in particular, increasing cytokine levels over time were predictive of mortality in a cohort of patients with underlying hematologic malignancies presenting with concern for pulmonary infection." (PMID 31428097, 2019). "Noteworthy, patients with hematological malignancies have increased serum levels of CCL2, IL‐6 and IL‐8 that have been associated with symptoms and with a poor prognosis." (PMID 40511387, 2025). "Expression of JAK1/2 and STAT3 in latently infected cells from both lines was suggestive of an IL-6 response axis (IL6(R)/JAK/STAT3) known to be activated in hematologic malignancies." (PMID 39446925, 2024). "A previous study observed elevated levels of IL-6, IL-8, and IL-10 in newly diagnosed hematological malignancies accompanied by pulmonary bacterial infections." (PMID 37114211, 2023). "FDA-approved agents for inflammatory diseases targeting the IL-6/JAK/STAT axis are being evaluated together with novel STAT3-specific inhibitors for the treatment of hematological malignancies and solid tumors." (PMID 37509339, 2023). "Simultaneous expression of IL-10, IL-8, and IL-6 is a decisive advantage in newly diagnosed hematological malignancies and pediatric patients." (PMID 36319826, 2022). "Idiopathic multicentric Castleman disease (iMCD) is a rare and life‐threatening haematologic disorder involving polyclonal lymphoproliferation and organ dysfunction due to excessive cytokine production, including interleukin‐6 (IL‐6)." (PMID 35488725, 2022). "In summary, our data indicate that IL-6, IL-8, and IL-10 are abnormally elevated in patients with lung bacterial infections in adult hematological malignancies." (PMID 34925324, 2021). "Multiplex cytokine assay indicates that mainly IL-6, IP-10 and MCAF changes are associated with FT3 serum levels, particularly in patients with coexistent hematological malignancies." (PMID 33794925, 2021). "IL6 promotes cell proliferation in other hematological malignancies and in solid tumors, as it is produced by a variety of cell types and is involved in immune response, inflammation and hematopoiesis." (PMID 34359576, 2021). "IL-6, IL-8 and IL-10 are abnormally elevated in patients with lung bacterial infections in adult hematological malignancies." (PMID 34925324, 2021). "In view of other people’s research and our results, we believe that cytokines, especially IL-6, IL-8 and IL-10, should be tested in patients with hematological malignancies." (PMID 34925324, 2021). "In several reports, an up-regulated IL-6/IL6R system has shown a prognostic impact in patients with hematologic malignancies and with solid tumors." (PMID 24886605, 2014). "In this context, it was notable that two of the five most stabilized genes, pik3cd and IL6 are already directly targeted by therapeutics in clinical trials of hematologic malignancies (NCT00710528, NCT00402181)." (PMID 19829692, 2009). "They maintain low levels of IL1B during CAR T cell therapy to minimize IL-6- and IL-1-associated cytokine toxicity and neurotoxicity without impairing therapeutic efficacy in patients with hematological malignancy." (PMID 38340727, 2024).
hematological malignancies (continued). "IL-6 and IL-8 are being researched more in children with hematological malignancies." (PMID 34925324, 2021). "Further research efforts are warranted to evaluate whether IL‐6 blockade via tocilizumab can alter the disease course in patients with hematological malignancies and Covid‐19." (PMID 32931637, 2020). "The objective of this study was to investigate the prognostic value of IL-6 and IL-8 as well as fungal biomarkers in blood and bronchoalveolar lavage fluid (BAL) for overall survival in patients with underlying hematological malignancies and suspected mold infection." (PMID 31428097, 2019). "This suggests that targeting Tet2/Hdac2-mediated gene-specific repression could be a novel therapeutic approach to decrease IL-6 signaling in patients with hematologic malignancies." (PMID 29181334, 2017). "IL-6 levels may also be affected by several kinase inhibitors that are currently in clinical use for hematologic malignancies, such as ruxolitinib, a JAK inhibitor in the treatment of MF and PV." (PMID 29181334, 2017). "However, there are currently few clinical trials testing IL-6 inhibitors in hematologic malignancies." (PMID 29181334, 2017). "IL-6, in the cellular context of KIT mutations, not only induces DJ-1 expression in mast cells, it promotes secretion of ROS into the extracellular space, a feature that has been linked to some hematological malignancies and to cell transformation in general." (PMID 27611333, 2016). "Furthermore, abnormally high expression of IL-6 and IL-8 may indicate poor mortality in individuals with hematological malignancies who have pneumococcal infection." (PMID 36319826, 2022). "Furthermore, studies have shown that a concentration of high IL-6 may be indicative of a poor prognosis in patients with solid or hematologic malignancies." (PMID 34335758, 2021). "Cytokines have been studied more in depth in hematological malignancies; however, in these studies, a noted association has been made that higher levels of interleukin 10 (IL-10) were found in BAL of patients who also had IPA or worst outcomes in patients with persistently elevated IL-6 and IL-8." (PMID 30687264, 2018). "Univariate analysis identified several factors associated with in-hospital mortality, including Voriconazole/Posaconazole use, IPA diagnosis, ICU hospitalization, hematologic malignancies, PCT, IL-6, and NEU%." (PMID 40376458, 2025). "In conclusion, we currently observe the kinetic changes of IL‐6, PCT, and CRP to investigate their role in initial antibiotic efficacy evaluation of FN patients with hematological disorder, confirming IL‐6 and CRP as the biomarkers." (PMID 38967137, 2024). "This study aims to investigate the early kinetics of interleukin 6 (IL‐6), procalcitonin (PCT), and C‐reactive protein (CRP) on initial antibiotic efficacy in hematological disorder patients with febrile neutropenia (FN)." (PMID 38967137, 2024). "This study confirmed IL‐6 and CRP levels, and the percentage change in IL‐6 as the biomarkers for initial antibiotic efficacy prediction in hematological disorder patients with FN." (PMID 38967137, 2024). "In hematologic malignancies, treatment of CRS often targets elevated cytokines (most elevated cytokines typically seen are IL-10, IL-6 and INF- γ) and is managed using corticosteroids interleukin-6 blockade." (PMID 36874119, 2023). "In the current study, we have successfully and safely applied CRISPR gene editing to disrupt GM-CSF expression in CART cells co-expressing IL6 and IL1 blockers in treating patients with refractory hematologic malignancy." (PMID 33907185, 2021). "Here we present a clinical investigation (ChiCTR2000032124; ChiCTR2000031868) of anti-CD19 and anti-BCMA CART (41BBζ) secreting an anti-IL6 scFv and IL1 receptor antagonist (IL1RA) in treating patients with hematologic malignancy." (PMID 34518515, 2021).